LDHA (lactate dehydrogenase A)
Diseases named in the same sentence as LDHA in open-access papers (continued):
Sharing a sentence is not in itself a finding about the gene and the disease.
breast cancer (continued). "For instance, chronic stress induced epinephrine promoted stem-like properties by lactate dehydrogenase A (LDHA) mediated metabolic rewiring to facilitate breast cancer progression." (PMID 37151872, 2023). "For instance, panepoxydone exerted protective mechanisms against breast cancer initiation and progression by suppressing lactate dehydrogenase A expression levels and reinducing lactate dehydrogenase B expression levels." (PMID 36771106, 2023). "Chronic stress-induced epinephrine promotes the development of breast cancer stem-like traits by rewiring the metabolism in a lactate dehydrogenase A (LDHA) dependent manner." (PMID 37051193, 2023). "Chronic stress-induced epinephrine promotes breast cancer stem cell-like properties via activation of lactate dehydrogenase A (LDHA) -dependent metabolic rewiring." (PMID 37773152, 2023). "In contrast, in vesicles with high levels of miR-7641, miR-7641 inhibited HIF-1α to downregulate the levels of HK2, GLUT1, and LDHA to suppress glycolysis in breast cancer." (PMID 37204526, 2023). "Kaempferol, found in tea and various fruit, downregulates LDHA expression in human breast cancer cells through inhibition of STAT3 activity." (PMID 37915411, 2023). "It is reported that Galloflavin can bind to free LDHA and inhibit glycolysis in breast cancer cells, thus acting as an anti-tumor agent." (PMID 36875841, 2023). "LDHA is abnormally expressed in many cancers, including pancreatic cancer, hepatocellular carcinoma, and breast cancer." (PMID 37233956, 2023). "In another study, circYY1 was found to upregulate the protein levels of HK2 and LDHA simultaneously in breast cancer cells and knockdown of circYY1 has a good tumor inhibitory effect." (PMID 37204526, 2023). "EGCG, the primary flavanol in green tea, inhibits LDHA and exhibits anti-cancer activity in pancreatic cancer cells, and it significantly slows the growth of breast cancer cells, triggering apoptosis through its action as an LDHA inhibitor." (PMID 37915411, 2023). "It suggested that TMEM105 enhanced the migration and invasion of breast cancer cells in an LDHA-dependent manner." (PMID 36737428, 2023). "As a sponge of miR-1208, TMEM105 upregulated LDHA expression by competitively interacting with miR-1208 in breast cancer cells thereby promoting glycolysis and BCLM." (PMID 36737428, 2023). "The overexpression of LDHA has been established in various solid cancers, including renal, pancreatic, non-small cell lung cancer, colorectal cancer, breast cancer, and other gynecologic cancers." (PMID 36072431, 2022). "In trastuzumab-resistant ErbB2-positive breast cancer cells, higher glycolytic activity is mediated by heat shock factor 1 and LDHA." (PMID 35328602, 2022). "For instance, LDHA overexpression reinforced cell proliferation and glycolysis in breast cancer cells." (PMID 36109751, 2022). "The HBXIP/lncRNA Hotair/LSD1 complex promotes the c-Myc-mediated transcription of cyclin A, eIF4E, and LDHA in the breast cancer cells." (PMID 34510316, 2022). "Previous studies claimed that the expression level of LDHA was increased in breast cancer, and LDHA expression was strikingly correlated with TNM stage and distant metastasis." (PMID 36109751, 2022). "In fact, they proved that miR-34a overexpression downregulates the LDHA level, thereby impeding glycolysis and hindering cell proliferation and metastasis in reprogramed breast cancer cells." (PMID 36230935, 2022). "They observed that miR 34-a directly binds to the 3′-UTR of LDHA and downregulates its expression in breast cancer." (PMID 36230935, 2022). "Since LDHA is a miR-34a direct target, it is negatively correlated with such miRNA in breast cancer." (PMID 35348905, 2022). "We confirmed the specificity of OVOL2, PKM2, and LDHA antibodies by immunohistochemical staining of breast cancer tissues or immunoblotting with cell lysates." (PMID 35896951, 2022).
breast cancer (continued). "LDHA inhibitors suppress proliferation of HER-2-overexpressing cells in breast cancer and increase sensitivity to drug therapy." (PMID 36059650, 2022). "According to the ISOexpresso database, the most common LDHA transcript in breast cancer cells is LDHA-203, which harbors a 357-nt 5’ untranslated region (UTR) as well as a 567-nt 3’UTR." (PMID 36418319, 2022). "Consistently, our data showed that the treatment of breast cancer cells with IGFBP6 significantly induced an increase in the mRNA expression of the LDHA, MCT1 and MCT4 genes." (PMID 35204157, 2022). "According to a recent study, LDHA also plays a significant role in acquired tamoxifen resistance in breast cancer by facilitating autophagy." (PMID 36059650, 2022). "Panepoxone, a monoterpenoid identified from Lentinus strigellus, reduced oxygen consumption, lactate production, and ATP synthesis in breast cancer cells via inhibiting LDHA." (PMID 36247675, 2022). "Independent studies using mouse models of breast cancer and melanoma have shown that depletion of lactate dehydrogenase A (LDHA) from tumor cells led to a dramatic increase in tumor-infiltrating T-cells and NK cells." (PMID 36505421, 2022). "Recent studies have shown that LDHA is over-expressed in various types of cancers, such as gastric cancer, breast cancer and pancreatic cancer." (PMID 36339566, 2022). "Overexpression of LDHA has been established in a number of malignancies, including hepatocellular carcinoma, breast cancer, and gastric cancer." (PMID 36564744, 2022). "The results of CCK-8, wound-healing and transwell assays indicated that ectopic Zeb1 expression promoted breast cancer cell viability and migration; however, treatment with the LDHA inhibitor OXM significantly weakened these effects." (PMID 35246504, 2022). "Oxamate, an inhibitor of LDHA, combined with paclitaxel-induced apoptosis in paclitaxel-resistant breast carcinoma (MDA-MB-435 and MDA-MB-231) cells by inhibiting cellular glycolysis." (PMID 35433453, 2022). "The role of lactate dehydrogenases in lactate metabolism has been studied extensively in breast cancer, and many have reported that LDHA overexpression is seen under hypoxic conditions and is associated with c-MYC gene overexpression and glutaminolysis." (PMID 34069745, 2021). "Conversely, LDHA knockdown in breast cancer cells that overexpress POU1F1 decreases tumor volume and [18F]FDG uptake in tumor xenografts of mice." (PMID 33714987, 2021). "In fact, interrogation of the epigenetic status of LDHA gene promoter in breast cancer cell lines showed a peak enrichment in H3K27ac, an epigenetic mark associated with higher activation of transcription." (PMID 33714987, 2021). "Several studies have shown that LDHA expression is abnormally high in various cancers such as liver cancer, breast cancer, and oral squamous cell carcinoma, and it is closely related to the malignant progression." (PMID 34307169, 2021). "The current study demonstrates that the POU1F1 transcription factor induces metabolic reprogramming by enhancing aerobic glycolysis of human breast cancer cells through transcriptional regulation of the LDHA gene." (PMID 33714987, 2021). "In breast cancer, lactate is produced mainly by the activity of lactate dehydrogenase A (LDHA), and it was studied to be used as a predictive marker for prognosis and overall survival in patients." (PMID 34069745, 2021). "EGC reduced LDHA activity in breast cancer (MCF-7 and MDA-MB-231) cell lines; notably, LDHA inhibition results from the dissociation of HSP90 from HIF-1α, resulting in HIF-1α proteasomal degradation." (PMID 33401572, 2021). "It was meaningful to find that LDHA expression was positively correlated with macrophages infiltration but negatively related with that in CD8+ T lymphocytes in breast cancer." (PMID 34178639, 2021).
breast cancer (continued). "The expression of Hsp70 and Hsp27 is induced by the transcription factor HSF1, which also regulates glucose metabolism and has been shown to increase the LDHA expression in breast cancer cells by binding to the LDHA promoter." (PMID 34359663, 2021). "LDHA inhibition can significantly restore the sensitivity of chemotherapy drugs: LDHA knockdown sensitizes oral squamous cell carcinoma cells and breast cancer cells to Taxol and lung cancer cells to low doses of paclitaxel via siRNA/shRNA." (PMID 34540667, 2021). "To investigate the role of LDHA in breast cancer progression, we analyzed the correlation of LDHA expression with the tumor clinical stages, metastasis, and survival according to TCGA database." (PMID 34178639, 2021). "LDHA has higher affinity for pyruvate and preferentially converts pyruvate to lactate, and is overexpressed in many malignant tumors, including breast cancer." (PMID 34158867, 2021). "Taken together, growth of 4T1 tumors was significantly suppressed in mice by using LDHA-specific inhibitor or shRNA, which indicated an important role of LDHA in mouse breast cancer progression." (PMID 34178639, 2021). "Firstly, the expression of LDHA in breast cancer tissues was much higher than that in adjacent tissues and correlated with the clinical progression and prognosis of breast cancer patients based on The Cancer Genome Atlas (TCGA) data set." (PMID 34178639, 2021). "This suggests an increased transcriptional activity of POU1F1 and consequently increased expression of LDHA in highly aggressive breast cancer cell lines." (PMID 33714987, 2021). "MΦ-derive lactate enhances tumor cell proliferation, which was in line with a previous study showing that in breast cancer cells reduced intracellular lactate was due to LDHA inhibition and diminished tumor growth." (PMID 34158867, 2021). "While derived from the 5’ end of the same stem ring, miR-30a-5p acts as a tumor suppressor in breast cancer by inhibiting the LDHA-mediated Warburg effect." (PMID 34307169, 2021). "Many studies have reported that upregulated LDHA promotes tumour metastasis and is correlated with poor prognosis in several cancers, including lung adenocarcinoma, breast cancer, HCC, gallbladder carcinoma, and renal cell carcinoma." (PMID 33407546, 2021). "LDHA gene expression was significantly upregulated in all breast cancer co-culture conditions relative to LEC cc." (PMID 33277521, 2020). "The overexpression of P4HA1 in cancer cells increases LDHA mRNA levels, and P4HA1 expression correlates with LDHA mRNA levels in human breast cancer tissue, which are consistent with our finding." (PMID 32635458, 2020). "In trastuzumab-resistant ErbB2-positive breast cancer cells, the improved glycolytic rate is regulated by heat shock factor 1 and LDHA and inhibition of glycolysis with 2-DG and the LDH inhibitor oxamate by-pass trastuzumab resistance." (PMID 32211323, 2020). "LDHA protein levels were increased for all breast cancer co-culture conditions matching qRT-PCR data." (PMID 33277521, 2020). "Immunohistochemistry confirmed that LDHA was primarily localized in breast cancer cells in contrast to LDHB, which was primarily localized in breast epithelial cells within benign breast tumors." (PMID 33353120, 2020). "Overexpressed LDHA is associated with poor prognosis in many tumors, including NSCLC, breast cancer, gallbladder carcinoma, and gastrointestinal cancer." (PMID 33344071, 2020). "Knockdown LDHA in neu-initiated mammary tumor cells decreases mitochondrial membrane potentials and cellular ATP levels, and therefore induces oxidative stress and apoptosis in these cancer cells." (PMID 32405344, 2020). "The HIF-1α-inducible expressions of GLUT1, HK2, PDK1, and LDHA were low in NRF2-silenced breast cancer cells and, accordantly, levels of hypoxia-inducible glycolysis metabolites such as G6P, F16P, GAP, and lactate were diminished by NRF2-silencing." (PMID 31078780, 2019).
breast cancer (continued). "Similar results emphasize the role of miR-34a, miR-34c, miR-369-3p, miR-374a and miR-4524a/b on the LDHA repression in colorectal cancer or breast cancer cells (miR-34a)." (PMID 31035592, 2019). "Among these, LDHA promoted glycolysis and cell proliferation of breast cancer MCF-7 and MDA-MB-231 cells, and its beneficial effects on glycolysis and cell proliferation can be impaired by miR-34a." (PMID 31989041, 2019). "All breast cancer tissues displayed higher LDHA and USP28 protein levels when compared with adjacent normal tissues." (PMID 30688660, 2019). "By establishing Taxol resistant breast cancer cell line, we found Taxol resistant cells exhibit upregulated LDHA and MCT1 expressions." (PMID 31367191, 2019). "For example, repression of LDHA by miR-34a inhibited the glycolysis and suppressed the growth of breast cancer cells." (PMID 31850191, 2019). "As a result, new medications are urgently needed to replace sodium oxamate for targeting LDHA and to reverse the chronic stress–derived breast cancer stem-like phenotype." (PMID 30688660, 2019). "The pharmacological and genetic inhibition of LDHA re-sensitized the TAM-resistant breast cancer cells to tamoxifen, but also inhibited the autophagy process therefore increasing cell death." (PMID 31737570, 2019). "In breast cancer, miR-30-5p inhibited the cell growth and metastasis through suppression of LDHA-mediated glucose metabolism." (PMID 31850191, 2019). "In this study, cantharidin does reduce the expression of GLUT1 but LDHA is unchanged in breast cancer cells." (PMID 31178738, 2019). "For example, lactate dehydrogenase A (LDHA) was found to promote breast cancer metastasis and its inhibitor oxamate was effective in inhibiting cancer cell invasion in multiple malignancies." (PMID 31531187, 2019). "Using an immunodeficient murine system, we showed that chronic stress–induced epinephrine promoted breast cancer stem-like properties via lactate dehydrogenase A–dependent (LDHA-dependent) metabolic rewiring." (PMID 30688660, 2019). "Quantitative RT-PCR data showed that silencing P4HA1 in breast cancer cells significantly reduced mRNA levels of LDHA and PDK1 under normoxia and hypoxia conditions." (PMID 30367042, 2018). "In breast cancer, Jin et al46 revealed that Y10 phosphorylation elicited LDHA activation, promoting cancer cell invasion and enhancing anoikis resistance." (PMID 30403008, 2018). "In trastuzumab-resistant ErbB2-positive breast cancer cells, increased glycolytic activity is mediated by heat shock factor 1 and LDHA and inhibition of glycolysis with 2-DG and the LDH inhibitor oxamate resensitizes resistant cells to trastuzumab." (PMID 30456204, 2018). "Inhibition of LDHA has an antiproliferative effect on cancer cells, such as breast cancer and liver cancer cells." (PMID 28915924, 2017). "It has long been known that LDHA levels in many human cancers including breast cancer, melanoma, renal cell carcinoma and gastric cancer are significantly higher than those in normal tissues." (PMID 28193910, 2017). "Abnormal LDHA expression is universal in many human cancers, such as pancreatic cancer, hepatocellular carcinoma, and breast cancer, suggesting that the overexpression of this gene promotes cancer development and progression." (PMID 28693517, 2017). "For example, taxol-resistant breast cancer cells exhibit higher LDHA expression and activity than do taxol-sensitive cells." (PMID 28137309, 2017). "Epigallocatechin, a key compound of SS, is reported to inhibit the lactate dehydrogenase A in breast cancer." (PMID 29234362, 2017). "In several breast cancer cell lines, inactivation of LDHA inhibits cell proliferation and induces apoptosis." (PMID 28430808, 2017).
breast cancer (continued). "In this study, we explored the critical roles of LDHA in aerobic glycolysis and cell proliferation in breast cancer cells and the mechanism of how miR-34a regulated LDHA and decreased its protein levels and activity." (PMID 26902416, 2016). "Among 22 breast cancer patients, approximately 80% (P = 0.0019, 17 of 22 patients) of tumor samples revealed an increase in LDHA expression levels." (PMID 26902416, 2016). "Taken together, these data indicated that LDHA influenced the aerobic glycolysis in breast cancer cells and was essential for breast cancer cell proliferation in vitro and in vivo." (PMID 26902416, 2016). "Compared with HME cell line (MCF-10A), we found that LDHA was upregulated in human breast cancer cell lines, especially in BT-483, MDA-MB-435, MDA-MB-231 and MDA-MB-468." (PMID 26902416, 2016). "We found that LDHA was upregulated in both breast cancer cell lines and clinical specimens using quantitative real-time PCR (qRT-PCR)." (PMID 26902416, 2016). "The purpose of this study was to investigate the expression, prognostic roles and function of LDHA in breast cancer." (PMID 26902416, 2016). "We found that concomitant high expression of 14-3-3ζ and LDHA predicts worse survival of breast cancer patients compared to high expression of either gene alone (P=0.00257 vs. P=0.0127 and P=0.0322)." (PMID 27150057, 2016). "Together, these results indicated that LDHA was a direct downstream target of miR-34a in breast cancer cells." (PMID 26902416, 2016). "Then, we detected the expression of LDHA in 22 pairs of breast cancer tissues (Breast cancer) and their matched normal adjacent tissues (Normal)." (PMID 26902416, 2016). "We demonstrated that LDHA upregulation led to increased glucose uptake and lactate production in breast cancer cells and significantly promoted cell proliferation in human breast cancer cell lines both in vitro and in vivo." (PMID 26902416, 2016). "In this study, we identified that 14-3-3ζ overexpression-mediated LDHA upregulation contributed to the metabolic switch toward glycolysis and cell transformation in early-stage breast cancer." (PMID 27150057, 2016). "To explore and confirm the role of LDHA in breast cancer cells, we performed the proliferation assay in breast cancer cell lines." (PMID 26902416, 2016). "Next, we detected the differences in metabolic parameters and we found that enhanced expression of LDHA largely influenced aerobic glycolysis in breast cancer cells, e.g., increased glucose uptake and lactate production." (PMID 26902416, 2016). "Repression of LDHA by miR-34a suppressed glycolysis and cell proliferation in breast cancer cells in vitro." (PMID 26902416, 2016). "Nevertheless, 14-3-3ζ/LDHA axis still provides prognostic values for overall survival of breast cancer patients." (PMID 27150057, 2016). "Our findings provide clues regarding the role of miR-34a as a tumor suppressor in breast cancer through the inhibition of LDHA both in vitro and in vivo." (PMID 26902416, 2016). "Here, we demonstrated a novel role of 14-3-3ζ in mediating early-stage breast cancer progression by upregulating LDHA expression and cellular glycolysis." (PMID 27150057, 2016). "In breast cancer, LDHA knockdown suppresses tumorigenicity through induction of oxidative stress mediated mitochondrial pathway apoptosis." (PMID 25983002, 2015). "For breast cancer, these genes included PLOD2 (procollagen lysyl hydroxylase 2, recently reported to be essential for hypoxia-induced breast cancer metastasis), and LDHA, a key enzyme in the terminal end of glycolysis." (PMID 25961905, 2015). "Abnormally expression of LDHA has been observed in many human cancers, such as pancreatic cancer, hepatocellular carcinoma, and breast cancer." (PMID 25983002, 2015). "We show that the level of LDHA was reduced in methyl sulfone-treated breast cancer cells under hypoxia and normoxia." (PMID 26536104, 2015).